PPP1R9B (protein phosphatase 1 regulatory subunit 9B)
Description:
Seems to act as a scaffold protein in multiple signaling pathways. Modulates excitatory synaptic transmission and dendritic spine morphology. Binds to actin filaments (F-actin) and shows cross-linking activity. Binds along the sides of the F-actin. May play an important role in linking the actin cytoskeleton to the plasma membrane at the synaptic junction. Believed to target protein phosphatase 1/PP1 to dendritic spines, which are rich in F-actin, and regulates its specificity toward ion channels and other substrates, such as AMPA-type and NMDA-type glutamate receptors. Plays a role in regulation of G protein-coupled receptor signaling, including dopamine D2 receptors and alpha-adrenergic receptors. May establish a signaling complex for dopaminergic neurotransmission through D2 receptors by linking receptors downstream signaling molecules and the actin cytoskeleton. Binds to ADRA1B and RGS2 and mediates regulation of ADRA1B signaling. May confer to Rac signaling specificity by binding to both, RacGEFs and Rac effector proteins. Probably regulates p70 S6 kinase activity by forming a complex with TIAM1 (By similarity). Required for hepatocyte growth factor (HGF)-induced cell migration.
Synonyms: PPP1R6; Spn; SPINO; PPP1R9
Tractability: Antibody: its Gene Ontology location is reachable by antibodies, with high confidence; UniProt places it where antibodies can reach, with medium confidence. PROTAC: ubiquitination databases record sites on it; its protein half-life has been measured.
Gene: Protein-coding gene on chromosome 17 (50,133,737 to 50,150,703, reverse strand). Ensembl gene ENSG00000108819.
Subcellular location: Cytoplasm, cytoskeleton; Nucleus; Cell projection, dendritic spine; Postsynaptic density; Synapse; Cell junction, adherens junction; Cytoplasm; Cell membrane; Cell projection, lamellipodium; Cell projection, filopodium; Cell projection, ruffle membrane
Gene Ontology:
Molecular function: protein binding; actin filament binding; protein phosphatase 1 binding; protein phosphatase inhibitor activity; actin binding; D2 dopamine receptor binding; kinase binding; protein kinase activity; protein-containing complex binding; transmembrane transporter binding
Biological process: cell migration; filopodium assembly; negative regulation of cell growth; actin filament organization; calcium-mediated signaling; cellular response to morphine; neuron projection development; regulation of cell cycle; regulation of cell growth by extracellular stimulus; regulation of cell population proliferation; regulation of exit from mitosis; regulation of opioid receptor signaling pathway; RNA splicing; actin filament depolymerization; cellular response to epidermal growth factor stimulus; cellular response to estradiol stimulus; cellular response to peptide; cellular response to xenobiotic stimulus; cerebral cortex development; developmental process involved in reproduction; hippocampus development; learning; male mating behavior; positive regulation of protein localization; positive regulation of protein localization to actin cortical patch; and 15 more
Cellular component: cytoplasm; filopodium; lamellipodium; nucleoplasm; plasma membrane; ruffle membrane; actin cytoskeleton; dendrite; postsynaptic density; protein phosphatase type 1 complex; adherens junction; cortical actin cytoskeleton; cytoplasmic side of dendritic spine plasma membrane; cytoskeleton; dendritic spine; dendritic spine head; dendritic spine membrane; dendritic spine neck; extrinsic component of postsynaptic membrane; glutamatergic synapse; growth cone; neuronal cell body; nucleus; plasma membrane bounded cell projection; spine apparatus; and 1 more
Genetic constraint (gnomAD): Loss-of-function variants: 17 observed, 55.27 expected, observed/expected ratio (o/e) 0.31, 90% interval 0.21 to 0.46. The synonymous counts are far from expectation, so gnomAD's model fits this gene poorly and the ratio says little. Missense variants: 870 observed, 916.28 expected, observed/expected ratio (o/e) 0.95, 90% interval 0.9 to 1. Synonymous variants: 505 observed, 408.43 expected, observed/expected ratio (o/e) 1.24, 90% interval 1.15 to 1.33.
Homologues: Orthologues: chimpanzee PPP1R9B (99% identical), macaque PPP1R9B (99% identical), pig PPP1R9B (97% identical), mouse Ppp1r9b (96% identical), dog PPP1R9B (96% identical), rat Ppp1r9b (96% identical), guinea pig PPP1R9B (96% identical), tropical clawed frog ppp1r9b (62% identical), zebrafish ppp1r9ba (62% identical), zebrafish ppp1r9bb (60% identical), Drosophila melanogaster Spn (33% identical), Caenorhabditis elegans nab-1 (22% identical). Paralogues in human: PPP1R9A (46% identical), SAMD14 (8% identical).
Diseases named in the same sentence as PPP1R9B in open-access papers:
PPP1R9B is named in the same sentence as 16 diseases in open-access papers, as found by Europe PMC text mining. Sharing a sentence is not in itself a finding about the gene and the disease. The quoted sentences say what the papers report.
HCMV infection (1 paper, 2024). "Our findings indicate that HCMV infection disrupts PP1 function through the temporal dysregulation of at least nine recognized regulatory subunits, PPP1R10, PPP1R7, YLPM1, PPP1R11, PPP1R9A, PPP1R8 (NIPP1), PPP1R9B, PPP1R12C, and URI1." (PMID 39772267, 2024).
mycobacterial infections (1 paper, 2022). "Of 15 prioritized in this study genes, four genes, namely GBP2, HEATR3, PPP1R9B and KDM6A, exhibited an elevated transcriptional level in whole blood, spleen or EBV-transformed lymphocytes, thus lending additional support to their role in increasing susceptibility to mycobacterial infections." (PMID 36338958, 2022).
Obesity (1 paper, 2015). Accumulation of substantial excess body fat. "The orthologs of Spn, protein phosphatase 1, regulatory subunit 9A (PPP1R9A) and protein phosphatase 1, regulatory subunit 9B (PPP1R9B), are associated with piglet birth weight and pig food intake and human obesity." (PMID 26375667, 2015).
osteosarcoma (1 paper, 2022). A usually aggressive malignant bone-forming mesenchymal neoplasm, predominantly affecting adolescents and young adults. "In order to determine which lncRNA was involved in osteosarcoma, lncRNAs including lnc-SELPLG-2:1, lnc-DDX47–3:1, lnc-ZNF77–165:3, lnc-SRSF2–9:2, lnc-SAMD11–1:1, and lnc-PPP1R9B-4:2 were detected by RT-qPCR to determine if their sequences were consistent with sequencing results." (PMID 36199080, 2022).
schizophrenia (1 paper, 2012). A major psychotic disorder characterized by abnormalities in the perception or expression of reality. "pH accounted for significant amounts of variance in parvalbumin (12%), somatostatin (36%), DLG4 (13%) and PPP1R9B (11%) in the schizophrenia group." (PMID 22545112, 2012). "Therefore, the correlation between increased TNFSF13 expression with increased PPP1R9B that we find might reflect less stability of synaptic spines, which in the context of schizophrenia could be detrimental to spine density." (PMID 22545112, 2012). "In order to put changes in TNFSF13 mRNA levels in the context of known schizophrenia neuropathology, we explored the relationship between levels of TNFSF13 mRNA and transcript levels of interneuron markers, somatostatin and parvalbumin, as well as spine markers, DLG4 and PPP1R9B." (PMID 22545112, 2012). "This suggests that DLG4 and PPP1R9B mRNA levels may not closely reflect the morphological changes observed in dendritic spines in patients with schizophrenia." (PMID 22545112, 2012).
tumor (3 papers, 2021 to 2025). "Furthermore, another amplified gene, PPP1R9B, has been associated with tumor progression and stemness in human tumors." (PMID 36352274, 2022). "PPP1R9B (SPN or NEURABIN‐2) is a tumor suppressor that affects tumor initiation and progression when the SPN domain that interacts with protein phosphokinase 1 (PP1) is mutated." (PMID 39778021, 2025). "Rationale: SPINOPHILIN (SPN, PPP1R9B) is an important tumor suppressor involved in the progression and malignancy of different tumors depending on its association with protein phosphatase 1 (PP1) and the ability of the PP1-SPN holoenzyme to dephosphorylate retinoblastoma (pRB)." (PMID 33537097, 2021).
cancer (2 papers, 2020 to 2023). A tumor composed of atypical neoplastic, often pleomorphic cells that invade other tissues. "Based on these findings, the ceRNA axes involving OIP5-AS1/hsa-miR-204-5p/BIRC5, DCP1A/hsa-miR-204-5p/BIRC5, and PPP1R9B/hsa-miR-204-5p/BIRC5 appear to play a crucial role in the progression of HCC, suggesting potential avenues for targeted therapeutic interventions in this type of cancer." (PMID 38283837, 2023).
PPP1R9B also shares sentences with these, for which no sentence is quoted: autism (1 paper); Cognitive impairment (1); influenza (1); lung carcinoma (1); major depressive disorder (1); microcephaly (1); neuroblastoma (1); neurodevelopmental disorder (1); Stroke (1).